BRCA1 (BRCA1 DNA repair associated)
Diseases named in the same sentence as BRCA1 in open-access papers (continued):
Sharing a sentence is not in itself a finding about the gene and the disease.
tumor (continued). "The analysis showed that the individual NGS platforms detected different numbers of BRCA1/2 alterations in the respective tumor sample." (PMID 35251494, 2022). "A limitation of the BRCA1/2-like classifier is that the test is less reliable on tumor tissue with admixture of many normal cells (i.e., tumor cell percentage <50%)." (PMID 35662281, 2022). "PARP inhibitors (PARPi) as single agents show promise in tumor treatment through the synthetic lethality they induce in cells with defects in BRCA1/BRCA2 and other components of the HR repair pathway." (PMID 36361678, 2022). "Tukachinsky and colleagues reported that with tumor tissue as reference, the positive percentage agreement for BRCA1/2 on cfDNA was 93%." (PMID 36551924, 2022). "For example, BRCA1/2-mutant tumours are more sensitive to DNA-damaging agents, including anthracyclines and carboplatin." (PMID 34728791, 2022). "In vivo anti‐tumour efficacy of pyridostatin and talazoparib on Brca1+/+ and Brca1−/−Tp53bp1−/− allografts." (PMID 35107878, 2022). "In the BRCA1/2 tumour-positive cohort, 26 cases had matching germline assessments, with 9 (35%) being a germline event and 17 (65%) representing a somatic event." (PMID 36011309, 2022). "A study combining olaparib and the CHK1 (checkpoint kinase 1) inhibitor prexasertib in a small group of patients, identified partial response in some HGSOC patients with BRCA1 mutant tumours who had demonstrated PARPi resistance." (PMID 36230543, 2022). "In contrast, VHIO179, a tumour carrying BRCA1 germline truncation and previously shown to be resistant to treatment with PARPi due to an inactivating mutation in the MAD2L2 (REV7) gene, was hypersensitive to pyridostatin." (PMID 35107878, 2022). "Highly mutated genes like BARD1, MALT1, BRCA1/BRCA2, EIF3K, PTEN, FGFR2, and MAP3K1 were also found to overlap with SVs of the tumor sample that were identified by one or more technologies in our study." (PMID 36514120, 2022). "The PALB2 gene product is a tumor suppressor and interacts with BRCA1 and BRCA2 to form a BRCA complex during double-strand break repair." (PMID 36359225, 2022). "The logistic-AFT mixture cure model provides a sophisticated statistical approach to explore consistent findings for elucidating the controversial issues of BRCA1 gene expression and aggressive tumor behavior." (PMID 34996912, 2022). "BRCA1/2 are tumor suppressors that are essential for the faithful repair of double-strand DNA breaks by homologous recombination." (PMID 35409110, 2022). "Previous studies also demonstrated that BRCA1 mutation and PARP1 activity also influence tumor metabolism." (PMID 35211121, 2022). "From the 52 tumor samples, variant analysis, large rearrangement analysis of HRR genes and assessment of promoter methylation of BRCA1 and RAD51C were performed on 52, 50 and 47 samples, respectively." (PMID 36294734, 2022). "For each tumor, we performed three different assays for BRCA1, and another three distinct assays for BRCA2." (PMID 35203410, 2022). "ATP11b expression in Brca1-MT primary tumors was only 10% that in WT tumors as revealed by quantitative PCR (qPCR) and was much lower in lung metastatic tumor tissues." (PMID 35025764, 2022). "Some tumours harbour functional BRCA1/2 genes (denoted BRCAwt) but still exhibit BRCAmut-like patterns of genomic instability." (PMID 35781107, 2022).
tumor (continued). "Specifically, the BRCA1/2 mutant subset of HGSOC are associated with higher neoantigen loads, elevated levels of tumour infiltrating lymphocytes (TILs), and increased expression of immune pathway genes." (PMID 36159999, 2022). "This study provides a comprehensive molecular understanding of HGSC tumor physiology and its dependence on BRCA1." (PMID 35292711, 2022). "In addition, pyridostatin triggers a type I innate immune response in the cells lacking BRCA1/2, which may potentiate its anti‐tumoral activity; (v) pyridostatin combination with the DNA‐PKcs inhibitor NU‐7441 and paclitaxel shows long‐term efficacy against BRCA1‐deficient tumours." (PMID 35107878, 2022). "A series of PARPi resistance mechanisms have been identified, mainly through preclinical studies using BRCA1/2‐mutant tumour cells and/or mice." (PMID 35567571, 2022). "Short mutations (single nucleotide or short insertions/deletions) in BRCA1/2 within the tumor (tBRCA*), which can reveal either gBRCA* or sBRCA* are estimated to be present in approximately 20–25% of cases." (PMID 35205846, 2022). "The effects of hypoxia on BRCA1 gene expression because hypoxia often occurs in tumor microenvironments were investigated." (PMID 35740092, 2022). "As a result, the researchers concluded that the domain of exons 11-13 plays a large role in the tumor suppressor function of BRCA1." (PMID 35740092, 2022). "This is exemplified with the FDA approval of PARP inhibitor olaparib for patients with germline BRCA1 or BRCA2 mutations in platinum-sensitive metastatic PDAC, further demonstrating the importance of deciphering the tumours at the molecular level." (PMID 35892707, 2022). "Intriguingly, when compared to group III, group IV exhibited a significantly reduced tumor burden, indicating that BRCA1 is required for TRIM44-induced cisplatin resistance in vivo." (PMID 35541909, 2022). "This is critical in determining one‐copy vs. total deletion or LOH in actionable tumor suppressor such as BRCA1, BRCA2, and PALB2, which are targetable only when inactivated biallelically." (PMID 34866317, 2022). "In contrast, M2 like macrophages with double-positive markers of F4/80 and CD206 were increased much more in Brca1-MT mammary gland, tumor adjacent and tumor tissues than that in WT mammary gland and tumor tissues, respectively." (PMID 35304461, 2022). "Four carriers of germline mutations had additional somatic DDR mutations in the primary tumor: ERCC4; BRCA1, ATM, FANCD2, and MLH1; BRCA1; and BRCA2, RAD50, and ATR." (PMID 36446793, 2022). "In this study, we demonstrated that no expression or low expression of ATP11B in conjunction with high expression of PTDSS2, which was negatively regulated by BRCA1, markedly accelerates tumor metastasis." (PMID 35025764, 2022). "After tumor formation, BRCA1 regulates mammary cell proliferation by interacting with the estrogen-estrogen receptor (E-ER) signaling pathway synergistically." (PMID 34996912, 2022). "Instead, these trials identify tumor positivity for PD-L1 and CD8 expression—features of the Brca1-deficient tumors studied herein—as biomarkers of a combinatorial response." (PMID 35082152, 2022). "This coincides with the results of a meta-analysis suggesting that patients with BRCA1 mutations will more probably have more TNBC and higher tumor burden." (PMID 35406503, 2022). "We discovered distinct immune microenvironments and divergent interactions between the immune subtypes and tumor and stromal metaclusters in tumors with BRCA1/2mut as compared to HRwt tumors." (PMID 35149709, 2022).
tumor (continued). "BRCA1 has been reported to have a plethora of roles in tumorigenesis from the start of a tumor, up to the regulation of epithelial-to-mesenchymal transition, cell motility, adhesion, invasion and ultimately metastasis." (PMID 35406503, 2022). "In the future, this will entail simultaneous tumor and blood BRCA NGS testing, and the evaluation of additional predictive biomarkers beyond BRCA1/2 gene alterations, as homologous recombination deficiency (HRD) signatures and immune biomarkers." (PMID 35406410, 2022). "An example of one of these patterns is illustrated by the methylation state of a CpG in the BRCA1-promoter region in relation to tumor fraction estimates derived from WGS." (PMID 36084090, 2022). "Among the 60 patients’ USC, 22 (36.7%) carried tumor HRR gene mutations (tHRRmt), with ATM, BRCA1, and BRCA2 being the most frequently mutated genes." (PMID 36428992, 2022). "BRCA1 mutations are more often associated with triple negative breast cancer (TNBC), whereas BRCA2 mutations are associated with HR-positive tumours." (PMID 35194731, 2022). "Tumors with BRCA1 and BRCA2 mutations have demonstrated increased susceptibility to PARP inhibitors given the tumor cells defects in chromosomal repair and error-free DNA double-stranded breaks." (PMID 36359225, 2022). "To this end, we established primary cell cultures from both an untreated fully BRCA1 promoter methylated TM01079 PDX tumor and one of the partially methylated TM01079 relapses emerging from the single cycle of cisplatin treatment." (PMID 35857626, 2022). "NG tumor samples not only possessed comparable rates of gene-level variation [BRCA1 (100%), BARD1 (41%), and BRCA2 (18%)] but also showed comparable variant frequencies." (PMID 36922933, 2022). "A growing body of literature has demonstrated that Brca1 functions in tumor suppression via DNA repair, genomic stability, cell cycle and transcriptional regulation during tumorigenesis and development." (PMID 36430332, 2022). "The extent of LOH in chromosome 17q varied across tumours with high HRD scores, with many showing hemizygous loss across BRCA1, RAD51C and RAD51D." (PMID 35039523, 2022). "First, current CDx should modulate their pipelines and integrate a deeper analysis of LRs, which have recently been shown to be an important part of BRCA1/2 alterations, leading to false negatives if tests are focused on tumor samples." (PMID 35205846, 2022). "Based on AKT1/AKT2 and AKT1/AKT3 ratios, we define four AKT classes which were related to patients’ survival, tumor morphology and BRCA1 expression." (PMID 35053468, 2022). "The BRCA1insC mutation results in the expression of a truncated BRCA1 missing the C-terminal BRCT repeat that interacts with phosphopeptides and promotes HR, which is necessary for tumor suppression." (PMID 36346676, 2022). "PALB2, a key partner of BRCA1/BRCA2, was involved in DNA damage repair and tumor suppression activity; thus, its mutation can lead to increased susceptibility to breast cancer." (PMID 35359350, 2022). "In the present study, the proliferating epithelial cells formed the most abundant tumor cell subpopulation, which was further enriched in the BRCA1/2mut tumors." (PMID 35149709, 2022). "The tumor suppressor BRCA1 interacts with PALB2 and BRCA2, and localizes to repair foci at DNA lesions similarly to MR64–66." (PMID 35501303, 2022).
tumor (continued). "TNBC tumours with BRCA-1 mutations were also observed to express more PD-1 and CTLA-4 compared with BRCA-1 normal tumours." (PMID 36531051, 2022). "This is especially imperative in determining one‐copy vs. total deletion or LOH of actionable tumor suppressors such as BRCA1, BRCA2, PALB2, and others for which biallelic inactivation would make them eligible for targeted therapy." (PMID 34866317, 2022). "Generally, BRCA1 has been well established as a tumor suppressor and functions primarily by maintaining genome integrity through DNA repair, especially when cells are exposed to oxidative stress." (PMID 35453307, 2022). "Over 9 years during which the patient received multiple lines of therapy, the tumor maintained BRCA1 LOH, copy number gains in ABCB10/11, high aneuploidy scores (≥13), MYC amplifications (CN ≥ 10) and PARP1 gains (CN = 4)." (PMID 36344544, 2022). "When comparing percent genome wide-LOH scores between BRCA1 and BRCA2 mutated tumours in both breast and ovarian cohorts, the scores were higher for BRCA1 than BRCA2 in ovarian (28 vs. 20, P < 0.001), and in breast (25 vs. 22, P < 0.001)." (PMID 34979999, 2022). "BRCA1 acts a majority in DNA repair, so this gene is important for tumorigenesis and tumor progression." (PMID 36547059, 2022). "In vitro and in vivo studies demonstrated that circPLEKHM3 played an anti-tumor role by sponging miR-9 to enhance the tumor-suppressive effect of BRCA1, DNAJB6, and KLF4, and consequently inactivated the AKT signaling in EOC." (PMID 36428803, 2022). "It is worth noting that Irofulven (MGI-114), a new cytotoxic anticancer drug with DNA damaging and MAPK activating properties, can also promote tumour cell apoptosis via ATM/CHK2 activation in the presence of BRCA1." (PMID 35801728, 2022). "Meanwhile, DNA repair defects due to BRCA1/2 mutation instigate immune signaling through the cGAS/STING pathway, and the inflammatory signaling provides both tumor-suppressive as well as tumor-promoting traits." (PMID 36741696, 2022). "Tumor cells with deficiency of HRR genes, especially BRCA1 and BRCA2, are sensitive to PARPi through the mechanism of synthetic lethality." (PMID 35241075, 2022). "Taken together, our data demonstrate that the common tumor-associated mutation in SF3B1, K700E, recapitulates many of the cellular deficits that are characteristic of loss of BRCA1/2." (PMID 35027467, 2022). "Those events overlap with many characteristic breast tumor suppressor genes such as BRCA1, BRCA2, CHEK2 with inferred CN lower than basal ploidy." (PMID 35681161, 2022). "Two germline PV/LPV, found in two different patients (1.2% of 170), were missed by tumor genotyping (one patient with BRCA1 large deletion and another patient with SNV in ATM)." (PMID 35326583, 2022). "Reflex tumour genetic testing of BRCA1/2 represents a major shift from the traditional germline genetic testing model for HGSOC patients, and the potential psychological impact for patients needs to be considered." (PMID 35418215, 2022). "If the relatively aggressive luminal B tumor expressed more BRCA1 transcripts, we expected high BRCA1 expression patients to have not only high proliferation marker expression but also rapid distant metastasis (DM)." (PMID 34996912, 2022). "Because the PTDSS2 protein level was stably elevated in both Brca1-MT mammary gland and tumor tissues in Brca1-MT mice, we conducted a promoter luciferase reporter assay, and the data revealed that the Ptdss2 promoter is negatively regulated by Brca1." (PMID 35025764, 2022). "The Oncomine database was used to analyze the mRNA levels of BRCA1/2 between tumor tissues and normal tissues." (PMID 35409110, 2022).
tumor (continued). "For example, a retrospective study of tumor specimens from 100 NSCLC patients treated with platinum-based therapy assessed the effect of low BRCA1 expression on response and survival." (PMID 36358724, 2022). "Since the first clone of the BRCA1 gene in 1994, variable cut transcripts were found as a “naturally occurring” event in both tumor and normal tissues by many studies." (PMID 35300412, 2022). "This study provides support for reflex tumour testing with a comprehensive NGS panel that includes BRCA1/2 and other HR genes in order to determine treatment eligibility and aid in triaging patients for germline testing and genetic counselling referrals." (PMID 36011309, 2022). "This study provides a first-look into the experience of newly diagnosed HGSOC receiving reflex BRCA1/2 tumour genetic testing." (PMID 35418215, 2022). "Previous studies have found that Breast Cancer 1 protein (BRCA1) is a tumor suppressor, and decreased expression of BRCA1 disrupts breast differentiation and increases the risk of BC5." (PMID 35132081, 2022). "Homologous recombination repair (HRR) is a key repair mechanism for DNA double-strand breaks, in which BRCA1/2 participates as key tumor suppressor genes." (PMID 35739489, 2022). "This study explains how BRCA1 aberration impacts the state of nascent tumor cells and their microenvironment." (PMID 35300412, 2022). "BRCA1/BARD1 also contributes to tumor suppression via the ubiquitination pathway and subcellular localization of BRCA1." (PMID 35650591, 2022). "This makes tumor cells defective in DNA homologous recombination and highly sensitive to platinum drugs, such as BRCA-1 gene mutant cells." (PMID 36278891, 2022). "Analysis of tumors after removal of an outlier p18−/−;Brca1+/− tumor, a p18+/− tumor and an outlier p18−/− sample, revealed that Tgfβr2 mRNA levels in p18−/−;Brca1+/− tumors were significantly higher than those in p18−/− tumors." (PMID 35236825, 2022). "The tumor suppressor genes BRCA1/2, which are found on chromosomes 17q and 13q, respectively, and encode factors that restrict cell development, were identified in the early 1990s." (PMID 35409110, 2022). "HRR deficiency was defined as a biallelic alteration in BRCA1/2, ATM, FANCA, PALB2, CHEK2, BRIP1, or HDAC2, assessed by a blood-based circulating tumor DNA (ctDNA) or tissue-based test." (PMID 35740437, 2022). "The tBRCT is known to present sequence-specific binding to phosphorylated peptides critical to BRCA1 tumor suppression function." (PMID 35837282, 2022). "Tumor cells with defective BRCA1 or BRCA2 lack the ability to perform HR efficiently thus sensitizing BRCA-mutant tumors to PARP inhibitors." (PMID 35869047, 2022). "The ability of BRCA1 to maintain genomic integrity is thought to be important for its role in tumor suppressor." (PMID 35387978, 2022). "With a tumor purity of 16%, the HRD sum score of 35 is higher than the corresponding median HRD-sum score of BRCA1/2 mutated tumors with similar purity levels." (PMID 36418296, 2022). "Altogether, the tumor cells were characterized by an abundance of proliferating epithelial cells in the BRCA1/2mut tumors, and EMT cells in the HRwt tumors." (PMID 35149709, 2022). "At the same time, our data also indicate that ATP11BloPTDSS2hi expression promotes tumor metastasis in BRCA1-WT tumors." (PMID 35025764, 2022). "We tested 24 tumor samples for BRCA1 and BRCA2 mRNA levels, normalized to the reference genes GUSB, POLR1E, and NUBP1." (PMID 35203410, 2022). "A single-arm, nonrandomized phase II study of talazoparib (NEOTALA) assessed patients with germline BRCA1/2 mutations and locally advanced HER-2-negative breast cancer (tumor size at least 1.5 cm)." (PMID 35877238, 2022). "Clearly, iNOS-mediated NO affects the tumor suppressor activities of both BRCA1 and BRCA2 as well as potentiating the expression of HER2." (PMID 35740092, 2022).